CD4 (CD4 molecule)
Diseases named in the same sentence as CD4 in open-access papers (continued):
Sharing a sentence is not in itself a finding about the gene and the disease.
Sjögren’s syndrome (continued). "This contrasts with an enrichment in DHSs specific to T cells that was reported using cytosines differentially methylated in CD4+ T cell studies of SLE and Sjögren’s syndrome." (PMID 30947741, 2019). "In Sjogren’s Syndrome, increased expression of TMEVPG1 lncRNA (IFNG-AS1—IFNG antisense RNA 1) was detected in CD4+ T lymphocytes and positively correlated with Th1 cell proportion among CD4+ T cells." (PMID 29751665, 2018). "T cells, in particular CD4+ T cells, play an essential role in the development of SLE and have previously been proposed as targets for the treatment of Sjögren’s syndrome." (PMID 27851974, 2016). "Quantitative analyses of CD4+ T cell subsets and of CD8+ T cells in the labial salivary glands from untreated patients with primary Sjögren’s syndrome revealed that activated CD8+ cytotoxic T cells (CD8+CTLs) were the most prominent T cells in these infiltrates." (PMID 36104369, 2022). "In addition to CD4+ cells, CD20+ cells (B cells) play an important role in the pathogenesis of Sjögren’s syndrome." (PMID 32545199, 2020). "In the peripheral blood of Sjögren syndrome (SS) patients, the frequency of CD4+ T cells was not significantly different from the frequency in healthy controls, and the absolute number of CD4+ T cells was decreased." (PMID 29312316, 2017). "They showed that in patients with untreated IgG4-RD compared with those with primary Sjögren’s syndrome, those with multi-centric Castleman’s disease, and HCs, the number of circulating Tfh2 cells (defined as CD3+CD4+CD45RA−CXCR5+CXCR3−CCR6−) was significantly increased." (PMID 28299186, 2017). "Clinical symptoms in keratoconjunctivitis sicca in both Sjögren’s syndrome and non-Sjögren dry eye are also known to be dependent on T cell activation, both CD4+ and CD8+T cells." (PMID 29068389, 2017). "Indeed, an expanded population of CD4+CD25low/−GITR+ Tregs is found in some patients with Sjogren's syndrome and SLE; expansion is observed in patients with inactive disease, suggesting that CD4+CD25low/−GITR+ Tregs participate in disease control." (PMID 25961057, 2015). "Even though cells defined in this way best resemble activated Tfh cells found in lymphoid structures, in some studies—including those studying Sjögren’s syndrome—(memory) CXCR5+ CD4 T cells without extensive further phenotyping are pragmatically also considered Tfh cells." (PMID 37569326, 2023). "There is also little information about the presence or role of CD4 T follicular helper cells (Tfh) in the MCMV-infected SG, but a few studies suggest an involvement in the formation of ectopic germinal centers in MCMV-infected SGs, or the presence of Tfh in the context of Sjögren’s syndrome." (PMID 34959486, 2021). "Recently, an increased frequency of CCR7+CD4+ T cells, which was shown to be closely correlated with EULAR Sjögren's syndrome disease activity index (ESSDAI), was found in pSS patients, suggesting that CCR7 might participate in the development of pSS by mediating the migration of CD4+ cells." (PMID 31068931, 2019). "Although the number of infiltrating CD4+ and CD8+ T cells was similar between patients with as Sjögren's syndrome DED and nonautoimmune DED, markers of T cell recruitment and activation were upregulated only in patients with nonautoimmune DED." (PMID 30158831, 2018).
celiac disease (95 papers, 2006 to 2026). An autoimmune genetic disorder with an unknown pattern of inheritance that primarily affects the digestive tract. "In humans, in vitro studies have shown that KIR+ CD8+ T cells can specifically eliminate gliadin-specific pathogenic CD4+ T cells in celiac disease through class I MHC–dependent cytotoxicity." (PMID 41438743, 2025). "Our data extend on previous work illustrating the dependence on CD8 Tregs to control EAE in a syngeneic model and the elimination of pathogenic gluten-responsive CD4 T cells in PBMCs derived from donors with celiac disease." (PMID 39559361, 2024). "This strong genetic association reflects the central role of CD4+ T cells as the HLA molecules associated with celiac disease bind specific gluten peptides that activate proinflammatory T cells." (PMID 36213409, 2022). "Of note, the identified IBD-associated CD4+ T cell subset here bears phenotypic similarities to a gliadin-specific subset recently identified in celiac disease and this phenotype was also found in multiple autoimmune diseases." (PMID 35812429, 2022). "The pathogenic immune response in celiac disease (CeD) is orchestrated by phenotypically distinct CD4+ T cells that recognize gluten epitopes in the context of disease‐associated HLA‐DQ allotypes." (PMID 35119226, 2022). "The strong major histocompatibility complex (MHC) class II association shows that CD4+ T cells play an important role in the pathogenesis of celiac disease." (PMID 34618841, 2021). "This particular variant is considered a risk variant for T1D and celiac disease, and correlated with impaired IL-2 signalling in CD4+ T cells as measured by decreased phosphorylation of STAT5 (pSTAT5) but also reduced PTPN2 expression." (PMID 33193091, 2020). "Pathogenic CD4+ T cells in celiac disease are DQ2- or DQ8-restricted, and T cell bound to DQ/gliadin tetramers are detectable using flow cytometry." (PMID 30319613, 2018). "This provides an explanation for why DQ2.5 and DQ2.2 celiac disease patients select distinct sets of gluten peptides for presentation to CD4+ T cells, which again explains why the two DQ2 variants have widely different risks for celiac disease." (PMID 25502872, 2015). "Class II major histocompatibility molecules confer disease risk in Celiac disease (CD) by presenting gliadin peptides to CD4 T cells in the small intestine." (PMID 24724018, 2014). "Coeliac disease (CD), an enteropathy caused by cereal gluten ingestion, is characterized by CD4+ T cells recognizing deamidated gluten and by antibodies reactive to gluten or the self-antigen transglutaminase 2 (TG2)." (PMID 24909383, 2014). "The pathogenic immune response in celiac disease is dependent on antigen (gluten peptides) presentation via major histocompatibility complex (MHC) class II molecules to CD4 positive T-cells." (PMID 21949668, 2012). "IFN-γ and IL-21 double-producing CD4+ T cells and also Th17 cells have been implicated in celiac disease as well." (PMID 21949668, 2012). "Moreover, these CD8+ T cells efficiently eliminated pathogenic gliadin-specific CD4+ T cells from the leukocytes of celiac disease patients in vitro." (PMID 35258337, 2022). "Celiac disease is caused by intolerance to cereal gluten proteins, and HLA-DQ molecules are involved in the disease pathogenesis by presentation of gluten peptides to CD4+ T cells." (PMID 25502872, 2015). "HLA-DQ molecules predispose to celiac disease by presenting gluten peptides to CD4+ T cells." (PMID 25502872, 2015). "Autoimmune diseases including coeliac disease (CD) can often be associated with significant target organ injury, but in contrast to acute infectious diseases, conventional functional assays are often not sufficiently sensitive to detect relevant peripheral blood antigen-specific CD4+ T cells." (PMID 34093551, 2021). "CD4 T-cell clonotypes have been found to remain in the peripheral blood of those with celiac disease for decades." (PMID 41158112, 2026).
celiac disease (continued). "In coeliac disease (CD), a prevalent CD4+ T‐cell‐driven autoimmune‐like enteropathy triggered by dietary gluten from wheat, rye and barley, the ELISpot assay has provided fundamental insights through comprehensive T‐cell epitope mapping of gluten." (PMID 41395355, 2025). "It significantly reduced gluten-specific CD4+ T-cell activation in the lamina propria, which is central to the pathogenesis of celiac disease." (PMID 40575215, 2025). "Gluten-specific CD4+ T cells with specificity to celiac disease play a central role in the pathogenesis of celiac disease and can be detected by functional T cell assays." (PMID 41374379, 2025). "In celiac disease, gliadin peptides activate CD4+ T cells, triggering release of pro‐inflammatory cytokines (TNF‐α, IFN‐γ, IL‐8) that parallel the cytokine cascade seen in PRES‐associated conditions." (PMID 40114993, 2025). "IL-15 can inhibit regulatory CD4+ T (Treg) cells, increase the number of IELs with a cytotoxic phenotype in celiac disease patients, and is also required for the development of villous atrophy." (PMID 38396767, 2024). "Once primed, the gluten-specific CD4+ T cells persist in coeliacs for decades thus explaining why coeliac disease is a life-long condition." (PMID 39307344, 2024). "A similar structural configuration, characterized by the preferential Vβ/Jβ usage, a nongermline encoded CDR3-β motif and biased TRAV pairing, was identified in gluten-specific, HLA-restricted CD4+ T cell clones in celiac disease." (PMID 38963700, 2024). "As CD4+ T cells are considered the drivers of immunopathology of coeliac disease, a comprehensive definition of the epitopes recognised by these gluten-specific CD4+ T cells will be essential." (PMID 39307344, 2024). "Celiac disease (CeD) is an autoimmune-like disorder mediated by CD4+ T cell response to deamidated gluten peptides that are selectively presented by disease-predisposing human leukocyte antigen (HLA) molecules (HLA-DQ2.5, HLA-DQ2.2, and HLA-DQ8)." (PMID 36696493, 2023). "In human celiac disease (CeD) HLA-DQ2.5 presents gluten peptides to antigen-specific CD4+ T cells, thereby instigating immune activation and enteropathy." (PMID 38135691, 2023). "CD4+ T cells specific for cereal gluten proteins are key players in celiac disease (CeD) pathogenesis." (PMID 36696493, 2023). "In Celiac disease, IE-adapted CD4+ T cells exhibit highly inflammatory Th1-like responses and contribute to tissue pathology, which is abrogated upon the removal of gluten from the diet." (PMID 37191720, 2023). "IL-10 has been shown to suppress infiltration of gluten-dependent cytolytic CD4+CD8αα+ IELs for potential prevention of celiac disease." (PMID 35493508, 2022). "Activation of gluten-specific CD4 T lymphocytes, which recognize gluten peptides, is the first factor initiating an immune response in celiac disease." (PMID 36742009, 2022). "The adaptive immune response of celiac disease (CeD) involves presentation of gluten peptides to CD4+ T cells by transglutaminase 2 (TG2) specific B cells." (PMID 35715890, 2022). "Using in vitro assays, it was demonstrated that CD8+KIR+Foxp3neg Treg suppressed gliadin specific CD4+ T cells isolated from patients with celiac disease." (PMID 35493508, 2022). "Gluten-specific CD4+ T cells drive the pathogenesis of celiac disease and circulating gluten-specific T cells can be identified by staining with HLA-DQ:gluten tetramers." (PMID 34618841, 2021). "Chronic inflammation of the small intestine in celiac disease is driven by activation of CD4+ T cells that recognize gluten peptides presented by disease-associated HLA-DQ molecules." (PMID 33796112, 2021). "The major instigating factor for the immune response in celiac disease is the activation of gluten-specific CD4+ T cells expressing T cell receptors that recognize gluten peptides presented in the context of HLA-DQ2 and DQ8." (PMID 33927210, 2021).
celiac disease (continued). "Gluten‐specific CD4+ T cells being drivers of celiac disease (CeD) are obvious targets for immunotherapy." (PMID 34495570, 2021). "While in celiac disease activated T cells CD4+ start producing mainly TH1 cytokines, as IFN-γ, in the atopic syndrome TH2 cytokines play the most important role." (PMID 33952340, 2021). "Improved blood tests assessing the functional status of rare gluten-specific CD4+ T cells are needed to effectively monitor experimental therapies for coeliac disease (CD)." (PMID 34093551, 2021). "In order to assess the precursor frequency of gluten-reactive CD4+ T cells in the active celiac disease lesion, we generated T-cell clones directly from unsorted lamina propria preparations of duodenal biopsies from nine individuals." (PMID 33796112, 2021). "We conducted unbiased full transcriptomic profiling of circulating gluten-specific CD4+ T cells from four untreated celiac disease patients by single-cell RNA-seq." (PMID 34618841, 2021). "A recent paper analysed gluten-specific CD4+ T cells in patients with celiac disease via gluten tetramer binding and found overlapping clonotypes in gut and peripheral blood, which also persisted over time." (PMID 33277543, 2020). "The pathogenesis of celiac disease is due to gluten-mediated activation of intestinal CD4+ T cells in the lamina propria." (PMID 31383006, 2019). "As Jabri and Sollid reported, the main feature of the molecular mechanism of celiac disease is related to the response of CD4 T cells to dietary gluten." (PMID 34466507, 2019). "Due to the effector role CD8+ and CD4+ T cells play in pathogenesis of celiac disease, the impact of anti-IL-15 treatment on small intestinal CD3+CD4−CD8+CD45+ and CD3+CD4+CD8−/+CD45+ T cells secreting IFN-γ was evaluated." (PMID 30050538, 2018). "Twenty six DQ2 and DQ8 restricted T-cell epitopes recognised by CD4 + T cells have been identified as being relevant for triggering coeliac disease." (PMID 28385663, 2017). "The immune response is abnormal in celiac disease with small intestinal epithelial damage via CD8+CD4- intraepithelial lymphocytes." (PMID 25926936, 2015). "Here, we studied intestinal iNKT cells in the context of celiac disease by molecular and cellular approaches, and found higher numbers of both total and CD4+ iNKT cells in the intraepithelial compartment of CD patients." (PMID 26529008, 2015). "In view of this evidence, display of TG2 in multivalent complexes decorated with gluten peptides and involvement of gluten reactive CD4 T cells thus appears as an attractive mechanism to explain the breaking of B-cell tolerance to TG2 in celiac disease." (PMID 26244572, 2015). "Celiac disease and T1D loci were also enriched for genes specifically expressed in CD4+ TEM cells (p = 1.43×10−5 and 1.29×10−4, respectively)." (PMID 24968232, 2014). "Lymphocytic infiltration in the lamina propria (LP), which is primarily composed of CD4+ Th1 cells and plasma cells, and increased numbers of intraepithelial lymphocytes (IELs), is a characteristic finding in active celiac disease (CD)." (PMID 24586509, 2014). "In agreement, DQ2 tetramer staining revealed that gluten-specific T cells appearing in blood of treated celiac disease patients after oral gluten challenge were predominantly CD4+CD62LnegCD38+." (PMID 23874626, 2013). "In celiac disease, gliadin acts as an antigen recognized by the CD4+ T cells and, moreover, has the ability to induce an activation of the innate immune response as well." (PMID 22629212, 2012). "Regulatory T cells (Tregs) also have a role in celiac disease, with recent studies showing increased numbers of circulating and mucosal CD4+Foxp3+ cells in individuals with active celiac disease, as compared to those on a gluten-free diet." (PMID 21949691, 2011). "As such, the immunopathology of celiac disease is well understood and allows researchers to focus on the specific population of CD4+ T cells that are responsible for inflammation." (PMID 21949691, 2011).
celiac disease (continued). "Increased levels of CD4+CD25+Foxp3+ cells in the circulation and mucosa are associated with active celiac disease." (PMID 21949691, 2011). "Based on the high association between human leukocyte antigens (HLA) and celiac disease (over 95%), it is thought that HLA-DQ2 positive antigen-presenting cells have gliadin peptides toxic to CD4+ T cells." (PMID 16722573, 2006). "Gliadin-reactive CD4+ T cells were isolated from the intestinal mucosa of patients with celiac disease." (PMID 16722573, 2006). "Gliadin peptide restimulation of CD4 T cells derived from human donors with celiac disease induced a corresponding expansion of purified celiac donor CD8 Tregs when cultured with CD4 T cells, consistent with data illustrating the expansion of CD8 Tregs in response to high-dose deamidated gluten." (PMID 39559361, 2024). "However, IE-adapted CD4+ T cells also have proinflammatory potential and can play a pathological role in a dysregulated response to dietary antigens, as is seen in Celiac disease." (PMID 37191720, 2023). "It has been shown that CD4+ T cells play a key role in the inflammatory response triggered by gluten, by driving and orchestrating the gut inflammation and tissue destruction in human celiac disease." (PMID 36246269, 2022). "Moreover, we developed an in vitro functional assay to test their regulatory functions on gliadin-specific disease-driving CD4+ T cells from patients with celiac disease (CeD) and to study the mechanisms of suppression." (PMID 35258337, 2022). "Gluten-specific CD4+ T cells are the key drivers for the pathogenesis of celiac disease." (PMID 34618841, 2021). "Celiac disease is driven by CD4+ T cells specific to gluten." (PMID 34495570, 2021). "Gluten-specific CD4+ T cells are drivers of celiac disease (CeD)." (PMID 33927715, 2021). "In celiac disease, also associated with DQB1*02:01 and DQB1*03:02, it is well documented that pathogenic, e.g., gliadin/avenin/glutenin-derived peptides, are recognized by CD4+ T-cells only when bound to HLA DQ2 or DQ8." (PMID 28534863, 2017). "Celiac disease (CD) is an intestinal inflammation driven by gluten-reactive CD4+ T cells." (PMID 23874626, 2013). "For celiac disease, the relative decrease of α-gliadins and γ-gliadins in indoor grains may be beneficial because these two types contain the highest numbers of known celiac disease-relevant epitopes recognized by CD4+ T cells." (PMID 40841578, 2025). "In addressing whether a food item will be dangerous to coeliac disease patients, the key issue to consider is whether the food item containing gluten will give rise to peptides that reach the small intestinal mucosa and stimulate CD4+ T cells." (PMID 39307344, 2024). "It follows that the main gluten peptides which people with coeliac disease should avoid are those which become targeted by TG2, and which are presented by the HLA-DQ2.5, HLA-DQ2.2 or HLA-DQ8 molecules to gluten-specific CD4+ T cells." (PMID 39307344, 2024). "Together, these results illustrate that CD8 Tregs derived from donors with celiac disease can directly and selectively kill gliadin-specific TCR-transduced CD4 T cells in a dose-dependent fashion." (PMID 39559361, 2024). "In celiac disease, HLA-DQ2.5 and HLA-DQ8.1 bind gluten peptides on APCs, some recognized by CD4+ T cells, prompting inflammation and tissue damage." (PMID 38202724, 2023). "The immunological model suggests that gluten-specific CD4+T-cells and cytotoxic intraepithelial T lymphocytes (IEL) play a key role in the development of celiac disease, as defined by the presence of anti-TG2 antibodies and villous atrophy." (PMID 36011206, 2022). "CD4+ and CD8+ T cells transcriptomes show extensive changes and we define a natural intraepithelial lymphocyte population that is reduced in celiac disease." (PMID 35995787, 2022).